IL1B (interleukin 1 beta)
Diseases named in the same sentence as IL1B in open-access papers (continued):
Sharing a sentence is not in itself a finding about the gene and the disease.
Middle East respiratory syndrome (5 papers, 2020 to 2021). A viral respiratory infection that is caused by the MERS coronavirus (MERS-CoV), which most often manifests with moderate to severe respiratory symptoms, including productive cough and shortness of breath, which can progress to pneumonia and acute respiratory distress syndrome. "In the research of the Middle East respiratory syndrome (MERS), caused by another coronavirus (MERS-CoV), cytokine genes of IL-6, IL-1β, and IL-8 can be markedly high." (PMID 33585031, 2021). "In the research of Middle East respiratory syndrome (MERS), caused by another coronavirus (MERS-CoV), cytokine genes of IL-6, IL-1β, and IL-8 can be markedly high." (PMID 32350134, 2020). "Moreover it has been widely demonstrated that in Middle East respiratory syndrome (MERS), a disease caused by another Coronavirus called MERS coronavirus, the cytokine gene expression of different ILs, including IL‐1β, can be markedly high." (PMID 33465283, 2021).
ocular hypertension (5 papers, 2020 to 2023). Abnormally high intraocular pressure. "To understand the underlying mechanism of PM2.5-related ocular hypertension, we measured the levels of proteins associated with the classic pyroptosis pathway (NLRP3/caspase-1/IL-1β/GSDMD) in aqueous humor outflow tissue." (PMID 33663554, 2021). "Stattic, a selective STAT3 inhibitor, administration resulted in a complete attenuation in the production of IL-1β and IL-6 in ocular hypertensive animals." (PMID 33628191, 2021). "Stattic administration (5 mg/kg, intraperitoneal, once a day for 7 days) fully attenuated the production of IL-1β and IL-6 in ocular hypertensive animals." (PMID 33628191, 2021). "The mRNA expression of IL-1β, TNF-α, Fas, IL-6, leukemia inhibitory factor, and IFN-γ was increased significantly in the retina of ocular hypertensive animals at day 7, post injury." (PMID 33628191, 2021). "In the current study, we have also shown that protein expression of IL-1β and IL-6 was remarkably increased in RGC and nerve fiber layers in ocular hypertensive animals, which was completely inhibited in SNC-121 treated ocular hypertensive animals." (PMID 33628191, 2021). "Furthermore, we have shown that elevated protein expression of TNF-α, IL-1β, and IL-6 were attenuated by SNC-121 treatment in ocular hypertensive animals." (PMID 33628191, 2021).
ocular toxoplasmosis (5 papers, 2019 to 2023). Ocular toxoplasmosis is an infection in the eye caused by the parasite, Toxoplasm a gondii. "It is now known that IL-10 levels are increased in ocular toxoplasmosis, while IL-1β is associated with more severe lesions." (PMID 37894166, 2023). "Within the Hernandez-de-los-Rios study, we performed a functional analysis of cytokine levels specifically in cases with ocular toxoplasmosis, and it was found that the A/A and G/A alleles resulted in significantly higher levels of IL-1β compared with the G/G genotype." (PMID 37894166, 2023). "Interleukin-6 (IL-6), a pro-inflammatory cytokine associated with pathogenesis of AMD, as well as in a model of ocular toxoplasmosis, and has been shown in vitro to be regulated by IL-1β, following IL-1β-dependent activation of the p38 MAPK/NF-kB pathway." (PMID 31379825, 2019). "Genotype and allele distribution for IL1β –511 and IL10 –1082 polymorphisms in individuals infected by Toxoplasma gondii with and without ocular toxoplasmosis and in individuals without the infection." (PMID 38983057, 2023). "A previous study showed that the expression of IFN-γ and IL-1β was not significantly influenced by ROP18 in peripheral blood mononuclear cells collected from patients with ocular toxoplasmosis." (PMID 33330132, 2020).
osteosclerosis (5 papers, 2022 to 2025). Abnormally high bone density. "Anti-IL-1β antibody completely neutralized IL-1β in bone marrow and plasma of VF mice and substantially reduced reticulin fibrosis and osteosclerosis." (PMID 36100613, 2022). "Anti-IL-1β antibody reduced reticulin fibrosis as well as the percentage of mice with osteosclerosis, and showed additive effects on both parameters with ruxolitinib." (PMID 36100613, 2022). "Moreover, the NF-κB inhibitor BMS-345541, targeting IKKα/β, has been shown to reduce extramedullary hematopoiesis, BM fibrosis, and osteosclerosis and to alleviate inflammation, as indicated by decreased levels of IL-1β and TNF." (PMID 41268532, 2025). "Moreover, the inhibition of IL-1β in JAK2V617F mutant mice by the anti-IL-1β monoclonal antibody 01BSUR also reduces MF and osteosclerosis." (PMID 41268532, 2025). "Spleen weight was slightly reduced in VF;IL-1β−/− recipient mice compared to VF, and histology of bone marrow revealed reduction in the grade of reticulin fibrosis as well as reduction in the percentage of mice with osteosclerosis." (PMID 36100613, 2022).
pericardial effusion (5 papers, 2012 to 2024). Fluid collection within the pericardial sac, usually due to inflammation. "Therefore we measured the concentrations of VEGF, bFGF, IL-1β, and TNF-α in pericardial fluid and serum from patients with inflammatory, nonmalignant pericardial effusion and patients without pericardial disease." (PMID 22577248, 2012).
peripheral arterial disease (5 papers, 2012 to 2024). A disorder of the arteries supplying the upper and lower extremity and the visceral organs. "This is of interest as in a model of peripheral arterial disease, autocrine IL-1β signalling promoted transcription of pro-angiogenic VEGF via activation of STAT3 and NF-kB." (PMID 38480935, 2024). "In addition, in peripheral artery diseases, activated platelets are enriched in MRP14, which increases their P-selectin expression and the formation of MPAs, and promotes the monocyte inflammatory profile by increasing IL1B, CCL2, and TNFA mRNA levels." (PMID 37279077, 2023). "In mice LPS and IL-1b administration directly induced GIP secretion and patients with peripheral arterial disease (PAD) showed higher circulating GIP levels compared to patients without PAD." (PMID 35123462, 2022).
PFAPA syndrome (5 papers, 2013 to 2024). An auto inflammatory syndrome characterized by recurrent febrile episodes associated with aphthous stomatitis, pharyngitis and cervical adenitis. "It has been recently observed that several cytokines are elevated during febrile episodes of PFAPA syndrome, primarily interferon-gamma, tumour necrosis factor, interleukin- (IL-) 6, and IL-1β." (PMID 26357457, 2015). "Recent study strongly suggests that IL-1β monocyte production is dysregulated in patients with PFAPA syndrome as a consequence of alteration in inflammasome activation probably linked to genetic defect in inflammasome related genes." (PMID 25821352, 2015).
plague (5 papers, 2010 to 2020). Plague is a severe bacterial infection caused by the gram-negative bacterium Yersinia pestis. "NLRP12, a member of the Nod-like receptor (NLR) family, is expressed in dendritic cells and neutrophils and recognizes Yersinia pestis infection, leading to inflammasome-mediated IL-1β processing and the production of mature IL-1β." (PMID 32670286, 2020). "The fact that so many of the Y. pestis T3SS components are participating in regulation of IL-1β/IL-18 release suggests that these effects are essential for maximal control of innate immunity during plague." (PMID 27911947, 2016). "Yersinia pestis, the causative agent of plague, harbors a T3SS which is particularly effective in suppressing innate immunity and release of pro-inflammatory cytokines IL-1β and IL-18, potent triggers of anti-bacterial responses." (PMID 27911947, 2016). "To identify the host mediators of inflammasome activation during pneumonic plague, we examined IL-1β production and Y. pestis virulence within the lungs of NLRP3-/-, NLRC4-/- and wild-type mice." (PMID 25781467, 2015). "Further, this activation occurred in the absence of all of the Yop effector proteins, indicating that the needle apparatus itself is sufficient for activating IL-1β during pneumonic plague." (PMID 25781467, 2015). "Y. pestis has been found to stimulate caspase-1 activation and IL-1β production in MΦs; however, this effect apparently was not dominant early in systemic plague." (PMID 23248776, 2012).
postmenopausal osteoporosis (5 papers, 2021 to 2025). Metabolic disorder associated with fractures of the femoral neck, vertebrae, and distal forearm. "The immune system plays a critical role in bone homeostasis and, consequently, in the pathophysiology of postmenopausal osteoporosis (OP) since estrogen deficiency induces the inflammasome and increases production of pro-inflammatory cytokines, such as IL-1β and IL-18." (PMID 36553538, 2022). "Inflammatory cytokines such as TNF‐α, IL‐1β and IL‐6 are elevated in postmenopausal osteoporosis and have been shown to play a role in the development of the disease." (PMID 38748896, 2024). "Tetrahydrocoptisine was found to modulate postmenopausal osteoporosis by directly interacting with disease-related proteins such as IL6, IL1B, and TNF, in addition to affecting disease-associated biological functions and indirectly interacting with other disease-related proteins." (PMID 39596387, 2024). "Both falcarindiol and tetrahydrocoptisine demonstrated direct interaction with pro-inflammatory cytokines IL6, IL1B, and TNF, key drivers of osteoclastogenesis and bone resorption in postmenopausal osteoporosis by activating inflammatory pathways linked to bone loss." (PMID 39596387, 2024). "In conclusion, we suggested that IL1β priming TMSCs has therapeutic potential for postmenopausal osteoporosis, which may improve bone density, restore bone homeostasis, and enhance anti-inflammatory capacity." (PMID 34115339, 2021). "Therefore, IL1β priming TMSCs can be a new therapeutic option for treating postmenopausal osteoporosis." (PMID 34115339, 2021). "IL1β priming can endow constant therapeutic efficacy with TMSCs, which may contribute to improve bone density and maintain bone homeostasis in postmenopausal osteoporosis." (PMID 34115339, 2021). "The direct interactions of rutin, beta-sitosterol, quercetin, norisoboldine, and hyperoside with key disease-related proteins such as TGFB1, TNF, IL1B, IL6, and CAT suggested that these compounds may modulate critical pathways involved in the pathology of postmenopausal osteoporosis." (PMID 39596387, 2024). "However, biological effects of systemically infused IL1β priming TMSCs in postmenopausal osteoporosis model have not been investigated." (PMID 34115339, 2021).
promyelocytic leukemia (5 papers, 2012 to 2024). "Two protein bands where detected, one of 24 kDa, corresponding to the common ASC variant and one of 20 kDa (ASC-b), corresponding to an ASC variant that enhances IL-1β secretion in human promyelocytic leukemia cells (HL60)." (PMID 27732661, 2016). "For example, 50 μM of 25HC induced IL-8 secretion in U937 human promyelocytic leukemia of neuronal cells; however, 0.1 μM of 25HC decreased LPS-induced IL-1β mRNA and protein and inflammasome activation in cholesterol-25-hydroxylase-defficient bone-marrow-derived monocytes." (PMID 39595101, 2024). "Arsenic trioxide (ATO), a therapeutic agent against acute promyelocytic leukemia (APL), demonstrated an immunomodulatory effect by inhibiting macrophage secretion of IL-1β." (PMID 36264639, 2022). "The characteristic hemorrhages of acute promyelocytic leukemia (APL) are caused in part by the high expression of tissue factor (TF) on leukemic cells, which also produce TNF and IL-1β, proinflammatory cytokines known to increase TF in various cell types." (PMID 28343272, 2017). "We were able to demonstrate a down-regulation of TLR2 mRNA expression after treating IL-1β prestimulated IVD cells with curcumin, which confirms findings in other cell types such as monocytic THP-1 cells, HL-60 promyelocytic leukemia cells and primary peripheral blood polymorphonuclear neutrophils." (PMID 22909087, 2012).
psychological distress (5 papers, 2020 to 2024). "Overall, the Intervention seems to have a psychological effect by decreasing the symptoms of psychological distress and this could have been a cause of the decrease in IL-1β in the experimental group." (PMID 36350802, 2022). "A recent study found that higher psychological distress indirectly predicted worse cognition through higher levels of IL-1β, TNF-α, and IL-4." (PMID 38840166, 2024). "The indirect effect size of psychological distress on cognitive function through IL‐1β, TNF‐α, and IL‐4 were 26%, 25%, and 24%, respectively." (PMID 36965094, 2023). "In all mediation models, the A path on behalf of the relationship between psychological distress and cytokine levels (IL‐1β, TNF‐α, and IL‐4) was significant and positive (=4.80, =4.70, =3.25, respectively; <0.05)." (PMID 36965094, 2023). "Using PROCESS, we investigated whether psychological distress predicted cognitive function based on MMSE through IL‐1β, TNF‐α, and IL‐4." (PMID 36965094, 2023). "Psychological distress is common and almost accompanied by the whole process of cancer, and its relationship with cytokines deserved further study though the indirect effect size of psychological distress on cognitive function through IL‐1β, TNF‐α, and IL‐4 is limited." (PMID 36965094, 2023). "The link between psychological distress and cognitive function as measured by the MMSE was also mediated by IL‐1β, TNF‐α, and IL‐4 (effect size: 26%, 25%, and 24%)." (PMID 36965094, 2023). "However, cytokine levels can be altered by infection and cancer treatment, and an extended follow‐up is required to assess the dynamic course of IL‐1β, TNF‐α, and IL‐4 with psychological distress." (PMID 36965094, 2023). "The indirect effect of psychological distress via IL‐1β, TNF‐α, and IL‐4 on the MMSE was significant and negative (=−0.34, =−0.32, =−0.32, respectively; 95% CI [−0.59 to −0.17], [−0.52 to −0.16], [−0.54 to −0.13])." (PMID 36965094, 2023). "In another case involving both psychological distress and a severe physical inflammatory insult, nerve compression trauma increased spinal cord IL-1β mRNA in control but not RMS animals." (PMID 33447663, 2020).
Pulmonary hemorrhage (5 papers, 2015 to 2026). Pulmonary hemorrhage is a bleeding within the lungs. "In 4T1 models, B. lactis V9 co-therapy mitigated αPD-1-induced uterine inflammation and pulmonary hemorrhage by downregulating IL-1α, IL-1β, and IL-17A while maintaining effector cytokines." (PMID 42273689, 2026). "Co-injection of recombinant Rv0888NS/MS with an MPO inhibitor remarkably decreased recombinant Rv0888NS/MS-induced pulmonary hemorrhage, infiltration of inflammatory cells, and release of inflammatory cytokines (IL-6, TNF-α and IL-1β)." (PMID 29670633, 2018).
Q fever (5 papers, 2017 to 2025). A bacterial infection caused by Coxiella burnetii. "In C. burnetii antigen-stimulated whole blood, a high proportion of monocytes from both controls (Group 1) and IGRA-positive donors with a clinical history of Q Fever (Group 5) produced TNFα (median 10.8% and 17.6%), IL-1β (median 55.8% and 66.6%) and IL-6 (median 43.3% and 55.5%)." (PMID 37885896, 2023). "Other cytokines also play a role in Q fever as TNF-α, IL-1-β, and IL-10 as well as IL-2 and the IL-12/IFN pathway does play a role." (PMID 32765448, 2020). "This was also the case for IL-1β when comparing QFS patients with CFS patients and asymptomatic Q fever seropositive controls, and TNFα when comparing QFS patients with CFS patients and healthy controls." (PMID 31088495, 2019). "It identified five hub genes (IL4, IL6, IL1B, CD28, and AKT1) that may contribute to the progression of Q fever by regulating immune responses." (PMID 41468478, 2025). "In our hands, previous stimulation experiments of PBMCs with LPS for 24 h did not result in a difference in IL-6, TNFα, or IL-1β production between CFS patients, QFS patients, asymptomatic Q fever seropositive controls, and healthy controls." (PMID 31088495, 2019).
retinopathy of prematurity (5 papers, 2018 to 2022). A bilateral retinopathy characterized by neovascularization, scarring, retinal detachment, and eventually blindness. "Although the major pro-inflammatory cytokine IL-1β participates in retinopathy induced by hyperoxia (a predisposing factor to retinopathy of prematurity), the specific role of antenatal IL-1β associated with preterm birth (PTB) in retinal vasculopathy (independent of hyperoxia) is unknown." (PMID 30089839, 2018). "Moreover, [(3R,4S)-Hgl3]-1 behaved like 1 in in vivo rodent models of preterm birth (PTB) and retinopathy of prematurity (ROP), respectively, delaying IL-1β-induced labor and curbing hyperoxia-induced vaso-obliteration." (PMID 33415098, 2020).
Sciatica (5 papers, 2013 to 2022). Pain in the lower back and hip radiating in the distribution of the sciatic nerve. "Another IL1B SNP (rs1143634) was associated with sciatica in the disc herniation subgroup." (PMID 35964023, 2022). "IL-1β, IL-10, TNF-α, and IL-17 have been detected in human patients with sciatica and could be considered potential serum, biopsy, or cerebrospinal fluid biomarkers." (PMID 33183347, 2020). "Additionally we have sought whether a biomarker panel based on TLR-induced IL-1β production by PBMCs can distinguish pain from non-pain states in two separate clinical pain populations (medication overuse headache and sciatica) to explore potential clinical utility." (PMID 24204973, 2013).
scleritis (5 papers, 2019 to 2024). Inflammation of the sclera. "Moreover, histocompatibility complex (MHC), TNF, IL1A, IL1β, IL2, IFNγ, and TNF were widely present in the top five disease signaling pathways, suggesting that these genes may be involved in the development of scleritis." (PMID 37063831, 2023).
scrapie (5 papers, 2012 to 2020). A fatal disease of the nervous system in sheep and goats, characterized by pruritus, debility, and locomotor incoordination. "A mammalian genome study identified IL1B gene polymorphisms that modulated scrapie (a type of neurodegenerative disease) susceptibility in sheep and goats, and found IL-1β expression in the cerebellum." (PMID 23199001, 2012). "We analysed several different interleukins, but only the expression IL1B was significantly changed in blood in the scrapie group; first downregulated at 16 wpi and then upregulated at 22 wpi." (PMID 30208891, 2018). "Over-expression of IL1β has been reported in several scrapie models but remains unaltered in others." (PMID 25136317, 2014). "In the current study, none of the target genes (GFAP, SAA3, CXCL10, CD14, S100A9, and IL1B) associated with the acute phase response and inflammation were differentially expressed in the hippocampus of animals with and without scrapie." (PMID 31924264, 2020). "Interestingly, several studies showed an upregulation of IL-1β transcripts in mouse scrapie, in naturally-occurring scrapie of sheep and in human Creutzfeldt-Jakob disease cases." (PMID 25671600, 2015).
Skin rash (5 papers, 2014 to 2022). A red eruption of the skin. "On the other hand, a study in Japan has reported that serum IL-1β was significantly lower in the patients with AESD with HHV-6 infection than in the controls with exanthem subitem, which may be relevant to the finding of our study." (PMID 35707033, 2022). "Some positive clinical correlations (weak to moderate) of interest need to be mentioned- IFN-γ and pain intensity, IFN-β, IL-1β individually and fatigue, TNF-α and headache, IL-4 and myalgia, IL-6 and skin rash." (PMID 25343623, 2014). "In children with active atopic symptoms (skin rash) within 1 year (N = 37), the expression of IL-1β was significantly higher than in children without atopic symptoms (p = 0.049)." (PMID 31548841, 2019).
small cell lung carcinoma (5 papers, 2006 to 2023). Small cell lung cancer (SCLC) is a highly aggressive malignant neoplasm, accounting for 10-15% of lung cancer cases, characterized byrapid growth, and early metastasis. "Conditions of IL-1β and hypoxia also promotes CXCL6 in cell lines from small cell lung cancer." (PMID 31824496, 2019).